ALK (ALK receptor tyrosine kinase)
Diseases named in the same sentence as ALK in open-access papers (continued):
Sharing a sentence is not in itself a finding about the gene and the disease.
tumor (continued). "In our previous paper, we reported that the ALK I1171S + G1269A compound mutant was sensitive to the second-generation ALK-TKIs ceritinib and brigatinib, and tumor regression was achieved in this patient after ceritinib treatment." (PMID 33627640, 2021). "MET amplification is also detected in other oncogene-addicted NSCLCs including those with ALK rearrangements, in which 15% of tumour biopsies from patients relapsing on next-generation ALK inhibitors detected MET amplification." (PMID 34898564, 2021). "Targeting this oncogenic signaling pathway in ALK+ ALCL largely inhibited the ability of PD-L1-mediated tumor immune escape when cocultured with PD-1-positive T cells and natural killer cells." (PMID 34503066, 2021). "Pharmacologic inhibition of DNA methylation using 5-Aza-2′Deoxycytidine was also efficiently delaying tumor formation in the ALK model when administered from 8 to 30 wk of age." (PMID 33310759, 2021). "Flow cytometry using surface staining of CD45 and CD30 and intracellular staining of ALK allowed the detection of circulating tumor cells with a sensitivity of 10−4 in one early study, whereas PCR techniques show a sensitivity of at least 10−5." (PMID 33921029, 2021). "Remarkably, a 14 day combined ATR/ALK inhibition therapeutic protocol completely ablated tumours in all ALK-driven-NB GEMMs treated." (PMID 34819497, 2021). "In terms of functional in vitro assays, authors reported an increase of phagocytosis capability of M2-BMDM MPEI/pCAR-IFN-γ treated cells for distinct ratios of BMDM: ALK+ target Neuro-2a tumor cell." (PMID 34977027, 2021). "ALK+ T cells were also present in spleens from 18-wk-old ALK tumor-free mice as well as ALK tumor mice." (PMID 33310759, 2021). "To investigate the molecular mechanisms associated with Dnmt1 deletion in ALK transgenic mice, we performed RNA-seq analyses of thymocytes isolated from Ctrl, KO, and ALKKO mice and compared it with our tumor RNA-Seq data." (PMID 33310759, 2021). "We assumed that if there are extra cell types in the ALK tumor replicas these additional cell types should be characterized through differentially expressed genes between the simulations and the real replicas." (PMID 33310759, 2021). "In the present study, we developed a novel ALK-targeting PI polyamide, CCC-003, in order to target the F1174L mutation of ALK, and investigated the compound’s anti-tumor activity." (PMID 34591871, 2021). "Crizotinib potentially stops the growth of the tumor by blocking the tyrosine kinase activity of ALK." (PMID 33466277, 2021). "The authors counted the copies of ALK L1196M, separately for epithelial- and mesenchymal-type tumor lesions." (PMID 33572278, 2021). "FISH analysis of tumor cells by using SPECC1L-ALK DNA probes showed a fusion of orange (ALK) and green (SPECC1L) into yellow signals." (PMID 34559836, 2021). "Herein, we show that systemic treatment with ALK inhibitor crizotinib before surgery can provide the potential to cure the initially inoperable tumor." (PMID 33816312, 2021). "The expression of PD-L1, CD8+ tumor-infiltrating lymphocytes (TILs) and ALK was determined by immunohistochemistry." (PMID 34249733, 2021). "Overall, the tumour‐derived S‐type cells prevented apoptosis in the N‐type cells via ALK‐independent STAT3 activation triggered by secreted factors." (PMID 33932101, 2021). "We used published ChIP-Seq datasets integrated in the LOLA software tool including murine ESC, T lymphocytes, and thymus for comparison with our DNA methylation profile of ALK tumor cells." (PMID 33310759, 2021). "Experiments of over-expression and knockdown of ALK in NB cell lines have demonstrated its role in tumor initiation and cell proliferation, angiogenesis migration and invasion." (PMID 34771690, 2021). "Strikingly, we observed an increase in quiescent DN cells (DN(Q)) and a slight decrease in SP CD4 and CD8 cells based on thymocyte-specific marker gene expression in ALK tumor samples." (PMID 33310759, 2021).
tumor (continued). "A phase I ceritinib dose-escalation study in ALK-activated tumours has been completed: twenty-two patients were enrolled, seven of whom were NBL patients." (PMID 34575503, 2021). "More specifically, the assessment of the ALK status with LB performed both at baseline or on tumor progression in patients treated with ALKTKI present certain advantages compared to tissue biopsies approaches." (PMID 33467720, 2021). "ALK tumor cells showed stronger hypermethylation in nearby CpGs (0–5 bp distance), most likely reflecting tumor specific CGI hypermethylation." (PMID 33310759, 2021). "Deregulated miRNAs have been observed in many cancers including ALK(+) ALCL with tumor suppressor or oncogenic functions." (PMID 33466277, 2021). "ALK-fusion oncogenic driver accounts for the tumor development in 3–5% of patients with lung adenocarcinoma." (PMID 33761908, 2021). "Tumor cell line data showed that lorlatinib (3rd generation ALK TKI) was a more potent drug than the previously administered crizotinib (1st generation ALK TKI)." (PMID 34769260, 2021). "Some of the mechanisms of resistance are sensitive to novel ALK inhibitors but after an initial tumor response, more or less long-term resistance sets in." (PMID 33467720, 2021). "We demonstrated the presence of p-ALK by IHC in almost half of the tumor samples included in our cohort (47.8%)." (PMID 34029351, 2021). "Tumor genomic testing revealed that 28 patients (37%) carried an EGFR mutation, and three (4%) had an ALK/ROS1 rearrangement." (PMID 33794813, 2021). "In most of these studies, patients whose tumor harbored oncogenic alterations (particularly EGFR mutations and ALK and ROS1 rearrangement) were excluded." (PMID 34208111, 2021). "In contrast to MCC tumor samples only two out of nine MCC cell lines showed only low ALK phosphorylation by immunohistochemistry." (PMID 34029351, 2021). "Together, these data suggest that ALK-induced transformation and lymphomagenesis involves the induction of additional oncogenic pathways and the repression of tumor suppressive genes." (PMID 33310759, 2021). "More than 20 different fusion partners of ALK have been described in different neoplasms, and their number is still increasing." (PMID 33237469, 2021). "We used genome-wide RNA sequencing (RNA-seq) to compare tumor cells in ALK transgenic mice with thymocytes isolated from age-matched wild-type mice." (PMID 33310759, 2021). "Other methods under investigation for ALK translocation detection are the CTC and circulating tumour-associated platelets." (PMID 34915883, 2021). "Supervised analyses revealed that using snoRNA U3 as a single marker was sufficient to discriminate between ALK+ and ALK− ALCL tumours." (PMID 34842767, 2021). "In what way exactly the mutual existence of ALK and EGFR compound mutations in NSCLC impacts tumor behavior still remains a matter of debate." (PMID 33572278, 2021). "Several pieces of evidence suggest that tumor cells of systemic ALK+ ALCL display features of Th17 and/or ILC3 innate lymphoid cells." (PMID 34503066, 2021). "Fluorescence in situ hybridization analysis confirmed the presence of ALK rearrangements, a finding which highlighted the malignant nature of the tumor and the need for surgical excision." (PMID 37206935, 2021). "Both the expression of total ALK and the presence of p-ALK correlated with tumor MCPyV positivity and, further, to a better survival." (PMID 34029351, 2021). "Keeping in mind, the diagnosis of an epithelioid GIST, tumor biopsies were sent to the Harvard Medical School Pathology department for second opinion, where the diagnosis of ALK positive EIMS was made." (PMID 37206935, 2021). "Interfering with the interaction between PD-L1-expressing tumour cells and T cells expressing PD-1 is an effective therapy for many cancers, and this includes cHL and ALK+ ALCL." (PMID 33413671, 2021).
tumor (continued). "In xenograft models derived from cells of an HR-NB patient with ALK mutations, the association of the PIM inhibitor AZD1208 and ceritinib shows significantly enhanced anti-tumor activity compared with the two agents used alone." (PMID 34885651, 2021). "ALK rearrangement results in abnormal EML4-ALK fusion tumor gene, which activates ALK tyrosine kinase, leading to inhibition of apoptosis and promotion of tumor cell proliferation." (PMID 34630126, 2021). "Sequencing analysis revealed that all sublines harboured the anaplastic lymphoma kinase (ALK) F1174L mutation, indicating that they were tumour derived." (PMID 33932101, 2021). "Despite early expression of ALK, the distribution of T-cell subsets was normal in 18-wk-old ALK tumor-free mice as compared with Ctrls." (PMID 33310759, 2021). "ALK L1196M primarily existed within the epithelial tumor cells, suggesting that EMT and ALK mutations co-exist as independent mechanisms of drug resistance." (PMID 34660278, 2021). "As a result, age < 40 years (p = 0.039, HR 0.32 (0.11–0.95)), ALK-positive tumor (p = 0.010, HR 0.24 (0.08–0.71), and MTX-based chemotherapy (p = 0.003, HR 0.17 (0.05–0.56)) were factors associated with a good prognosis." (PMID 34503168, 2021). "The only ALK-rearranged tumor occurred in the minor salivary gland of the upper lip of a 73-year-old female." (PMID 33237469, 2021). "Our review of the literature on IMT and other kinase fusions revealed, in addition to ALK rearrangements, the potential association of ROS1, NTRK, RET, or PDGFR beta alterations with the tumor." (PMID 34011083, 2021). "In fact, potential ALK rearranged tumor cells release RNA into the blood stream by a variety of different vehicles, such as exosomes." (PMID 33467720, 2021). "As expected, ALK tumor cells showed significantly higher proliferation rates than thymocytes of Ctrl, KO, and ALKKO mice." (PMID 33310759, 2021). "The major question rising due to our study is why majority of the MCC cell lines lack ALK phosphorylation although patient derived tumor samples display p-ALK positivity by IHC." (PMID 34029351, 2021). "Constitutively active ALK is a clinically relevant oncogene because it ignites several downstream molecular pathways, driving malignant transformation and promoting tumor cell survival and proliferation." (PMID 34272360, 2021). "Overall, the clinical effect of sequential ALK-TKI therapy was mild in terms of the tumor response and short response duration." (PMID 34036223, 2021). "A high frequency of solid growth or mucus patterns in ALK-positive tumours was observed in the present study." (PMID 33707479, 2021). "Overexpression of ALK protein has been reported for many different types of cancer cell lines and human tumour samples." (PMID 34199079, 2021). "In ALK rearrangement NSCLC, SHP2 inhibitors combined with ALK inhibitors showed aggressive anti-tumor effect than a single drug in vivo and in vitro, and reversed the resistance of ALK inhibitors." (PMID 34217295, 2021). "Pretreatment ALK antibody titers are inversely correlated with stage of disease, amount of circulating tumor cells, and cumulative incidence of relapse in lymphoma." (PMID 33672007, 2021). "Using a cut-off value of four CTCs, ALK detection using CTCs had a sensitivity and specificity of 100% and had a 99.99% correlation with tumor biopsy analysis." (PMID 34680298, 2021). "Hypermethylated promoter regions in ALK tumor cells showed strong enrichment of binding sites for proteins associated with chromatin remodeling in ESC, in particular PRC associated proteins including CBX7, EZH2, MTF2, PHF19, RING1B, RNF2, and SUZ12." (PMID 33310759, 2021). "The addition of recombinant proteins to the tumour cells treated with the ALK inhibitor partially enhanced cell viability." (PMID 33932101, 2021).
tumor (continued). "Subsequently, these tumor cells show an increased frequency of signature 18 and 36 related genomic aberrations that lead to additional defects in tumor evolution associated pathways like RAS-MAPK and ALK." (PMID 34479993, 2021). "Ensartinib is a crizotinib-analogue that inhibited ALK phosphorylation in two cell lines and delayed tumour growth in a PDX model." (PMID 34575503, 2021). "We analyzed thymocytes isolated from thymi of 6- and 18-wk-old wild-type and ALK tumor-free mice, as well as tumor cells from ALK mice that had already undergone transformation." (PMID 33310759, 2021). "At present, there are approved drugs for lung cancer, targeting tumor cells with mutated EGFR, ALK and ROS1 fusions, and mutated BRAF." (PMID 34217228, 2021). "Diagnostic tumor samples were available from 1,092 HR-NBL1/SIOPEN patients to determine ALK amplification status (n = 330), ALK mutational profile (n = 191), or both (n = 571)." (PMID 34115544, 2021). "Remarkably, a 2-week combined ATR/ALK inhibition protocol leads to complete tumor regression in two independent genetically modified mouse NB models." (PMID 34819497, 2021). "Congruently, immunohistochemical analysis of the tumor metastasis in the lymph node showed ALK overexpression in the tumor cells, indicative of the functional nature of this fusion gene." (PMID 33878728, 2021). "These patients are treated with antiangiogenic multitarget tyrosine kinase inhibitors including lenvatinib and sorafenib, and specific inhibitors for BRAF-, MEK- or ALK-mutant tumours." (PMID 34062862, 2021). "For instance, in the ATC case study by Godbert and colleagues, a patient is reported with an ALK rearrangement in both its well-differentiated part as well as anaplastic part of the tumor." (PMID 33878728, 2021). "Out of 182 SGCs we screened by IHC, only eight samples expressed ALK in more than 10% of tumor cells with moderate to strong staining intensity." (PMID 33237469, 2021). "When ALK is expressed in spitz tumours, the tumours have a typical amelanotic look, and their development pattern is characterized by crossing fascicles." (PMID 35356629, 2021). "Consecutive tumor re-biopsies performed in patients receiving ALK inhibitors sequentially allowed the molecular basis for tumor evolution in EML4-ALK NSCLC to be determined." (PMID 33922215, 2021). "The anaplastic lymphoma kinase (ALK) protein is encoded be the ALK gene, which is rearranged in 3–7% cases of NSCLC and is recognized by the immune system as a tumor antigen." (PMID 33672007, 2021). "This patient was treated with the ALK inhibitor lorlatinib after matching tumor cell line data showed that lorlatinib was a more potent drug than the already administered crizotinib." (PMID 33878728, 2021). "These mutations usually occur in older patients (median age of 72 years) with a higher percentage of ever-smokers compared to patients with tumours harbouring other oncogenic alterations such as EGFR/ALK/ROS1." (PMID 34898564, 2021). "At disease progression on ALK-TKIs, genomic re-profiling of tumor biopsies is needed to portray the full spectrum of drug resistance and identify resistant heterogeneous tumor cell subpopulations." (PMID 34272470, 2021). "ALK is a key regulator of tumor cell growth and survival, and this translocation results in increased activation of the signaling pathway, promoting oncogenic cell proliferation and survival." (PMID 35008185, 2021). "All the genes within the detection range are included in the TMB (tumor mutation burden) calculation, excluding the kinase region mutations of EGFR and ALK, and the total number of CNV and fusion." (PMID 34168983, 2021). "Two cases of ALK rearrangement were detected in the tumor resection group, and one case in the open-close group." (PMID 33888088, 2021).
tumor (continued). "Combinations showed strong synergism in different ALK-dependent cell lines and better tumor growth inhibition in mice." (PMID 34503232, 2021). "In contrast, the EML4–ALK21S mutant group showed a significantly impaired tumor growth and dramatically decreased tumor sizes and weights, despite of comparable ALK expression." (PMID 33976114, 2021). "When compared with ALK tumor samples, ALKKO was similar to KO and Ctrl samples and showed a high degree of deregulation with 2,819 genes up- and 1,355 genes down-regulated." (PMID 33310759, 2021). "It is consistent with the indolent clinical behavior characteristics of this tumor as was also reported in another case of ALK-positive IC." (PMID 33237469, 2021). "The reduced expression of DUSP22 has been identified in TCL and this phosphatase likely behaves as a tumor suppressor gene in ALK- ALCL." (PMID 34572893, 2021). "Using this systems authors proposed to target ALK tumor-antigen as well as to reprogram TAMs to acquire pro-inflammatory properties inducing adaptive immune T cell responses." (PMID 34977027, 2021). "Alternatively, ALK-vaccine in combination with anti-PD-1/PD-L1 ICI has shown efficacy in preclinical models by overcoming adaptive mechanisms of tumor immune evasion." (PMID 33806977, 2021). "In T/natural killer (NK) cell neoplasia, PD-L1+ tumour cells were frequently found in anaplastic lymphoma kinase (ALK) + and ALK− systemic anaplastic large cell lymphoma (sALCL), occasionally in PTCL-NOS, and rarely in AITL." (PMID 34742294, 2021). "It revealed that the tumor harbored an echinoderm microtubule-associated protein-like 4 (EML4) and ALK fusion gene." (PMID 34064158, 2021). "The expression levels of ALK showed a gradual increase from 6 to 18 wk and were highest in tumor cells compared with untransformed thymocytes." (PMID 33310759, 2021). "Positivity for ALK IHC staining was denoted by the presence of strong granular cytoplasmic staining in any percentage of positive tumor cells using VENTANA ALK (D5F3) CDx Assay." (PMID 34559836, 2021). "Crizotinib has made significant progress in treating NSCLC with ALK-rearrangement, but with its extensive use, tumor cells develop drug resistance and become less and less sensitive to the treatment." (PMID 34630126, 2021). "The anaplastic lymphoma kinase (ALK)-rearranged upregulated PD-L1 expression and promoted tumor immune escape." (PMID 33653420, 2021). "Annotation of differentially methylated CpGs revealed that ALK tumor samples mainly gained DNA methylation in promoter regions, CGIs and shores, whereas intergenic and inter-CGI sites preferentially lost methylation." (PMID 33310759, 2021). "Early analyses showed response in ALCL and IMT tumours; however, only one NBL patient, who was harbouring an ALK F1174L point mutation, showed partial response with tumour shrinkage in the retroperitoneum but with simultaneous disease progression in the CNS." (PMID 34575503, 2021). "The robust inhibition of NB cell lines by ATR inhibition was confirmed in a xenograft NB model, where BAY 1895344 monotherapy treatment was as effective as the third-generation ALK TKI lorlatinib in reducing tumour growth." (PMID 34819497, 2021). "GKRS induced significantly satisfactory local tumor control in driver gene mutation-positive tumors but GKRS-related complication frequency was higher, especially in ALK-positive NSCLC patients." (PMID 35047245, 2021). "It has been demonstrated that 5-aza-Cdr showed strong antineoplastic activity in anaplastic cell lymphoma (ALCL), causing apoptosis and cell cycle arrest in vitro and in vivo and inhibiting ALK + tumour growth in vitro." (PMID 33160401, 2020). "Reduction in the size of the tumor (~2 cm) has been noted post 3 months of therapy, which points towards the positive ALK reactivity seen in this tumor." (PMID 30632123, 2020).